MYH7 (myosin heavy chain 7)
Diseases named in the same sentence as MYH7 in open-access papers (continued):
Sharing a sentence is not in itself a finding about the gene and the disease.
skeletal myopathies (14 papers, 2016 to 2025). "Recent studies have implicated the destabilization of the OFF state of MYH7 in the pathogenesis of skeletal myopathy as well." (PMID 39192034, 2024). "In contrast, skeletal myopathies caused by MYH7 mutations are rare, and the causal mutations are predominantly located in the rod domain." (PMID 35854315, 2022). "MYH7 mutations can also cause skeletal myopathies, since MYH7 is expressed in slow type 1 skeletal muscle fibers as well (reviewed by Oldfors)." (PMID 35269675, 2022). "MYH7-related skeletal myopathies are extremely rare, and the vast majority of causal variants in the MYH7 gene are predicted to alter the rod domain of the of ß-cardiac myosin molecule, resulting in distal muscle weakness as the predominant manifestation." (PMID 35854315, 2022). "The causative mutations in the MYH7 gene can occur in all three domains of the protein (head, neck and rod) and the resulting phenotype, which is wide, including cardiomyopathies, skeletal myopathies and both, is related to the affected region." (PMID 32456280, 2020). "More findings in genetic variation are needed to extend knowledge of mutations in the MYH7 gene linked to skeletal muscle disorders." (PMID 31068177, 2019). "More findings in genetic variation would extend knowledge of mutations in the MYH7 gene linked to skeletal muscle disorders." (PMID 31068177, 2019). "This study expands our clinical and molecular knowledge of MYH7 rod mutations causing skeletal myopathies, and highlights the importance of discussing disease penetrance during genetic counseling." (PMID 27519903, 2016). "The clinical spectrum of skeletal myopathies associated with MYH7 mutations is variable but is always associated with muscle weakness." (PMID 27519903, 2016). "Our study identified two novel mutations in the MYH7 rod domain, and expands the clinical spectrum of skeletal myopathies associated with MYH7 mutations." (PMID 27519903, 2016). "This study expands our clinical and molecular knowledge of MYH7 rod mutations causing skeletal myopathies, and underscores the importance of discussing disease penetrance during genetic counseling." (PMID 27519903, 2016). "Alterations in the MYH7 gene can cause cardiac and skeletal myopathies." (PMID 35854315, 2022). "Interestingly, we reported two cases of DCM and skeletal myopathy associated with MYH7 variants." (PMID 37240454, 2023). "Weakness limited to axial/proximal muscle groups is exceptionally rare in MYH7-related skeletal myopathies." (PMID 35854315, 2022). "Three studies of larger cohorts of patients with MYH7-related skeletal myopathies suggest a continuum of clinical manifestations." (PMID 35854315, 2022). "Defects of the MYH7 gene mainly result in myopathic cardiac diseases and skeletal myopathies including distal myopathy and other skeletal muscle abnormalities caused by thick filament accumulation in the sarcomeres." (PMID 28927399, 2017).
tumor (13 papers, 2016 to 2025). "Only the BCOR‐ITD was included in clone 1, whereas three clade mutations (FLT1, JAK2, and MYH7) were additionally detected in relapsed tumor samples (clones 2, 3)." (PMID 34967151, 2022). "At the time of diagnosis, the tumor cells had four distinct SNVs in USP54, GABRA3, KRAS and SETD2, while the relapsed tumor acquired four additional unique mutations in MYH7, NYNRIN, ODZ1 and ZIC3." (PMID 26527318, 2016). "Overall, we identified MYH7 as a novel diagnostic marker with a high diagnostic accuracy for PAs, and MYH7 may be associated with a tumor-suppressive microenvironment through promoting the exhaustion of immune cells." (PMID 40709170, 2025). "Myosin genes MYL1, MYL2, MYH2, and MYH7 were proved significantly down-regulated but as unfavorable prognostic markers and related with tumor stages or grades in HNSCC." (PMID 37679666, 2023). "There is a statistical significance of MYL1 or MYH7 promoter methylation level between normal tissues and tumor stage 1–4 or grade 1–4." (PMID 37679666, 2023). "MYH6 and MYH7, both on 14q11.2, were expectedly co-amplified and deleted in the same tumor samples with significant missense and truncation mutations distributed throughout both genes." (PMID 33217970, 2020). "This indicated that the expression of MYH7 aggravated the exhaustion of antitumor immune cells for a tumor-suppressive microenvironment, which may contribute to the aggressive phenotype of PAs." (PMID 40709170, 2025).
cardiovascular disease (10 papers, 2015 to 2024). "A reduction of the Myh6/Myh7 expression ratio is a well-established molecular marker of maladaptive cardiac remodeling and a target of therapeutic intervention to contrast cardiovascular disease evolution." (PMID 32987653, 2020). "Overall, we identified 5 reportable variants classified as KP or EP in the DSP, MYH7, and FBN1 genes, which have been reported to cause different types of cardiovascular diseases." (PMID 30217213, 2018). "Moreover, genes associated with human cardiovascular diseases, such as TNNT2, LMNA/C, TBX5, MYH7, ANKRD1, and NKX2.5, were also knocked-out by TALENs in human iPSCs to build cardiovascular disease models." (PMID 37626665, 2023).
genetic disorder (2 papers, 2020 to 2023). "HCM is a recognized genetic disorder most often caused by mutations involving myosin-binding protein C (MYBPC3) and β-myosin heavy chain (MYH7) which are responsible for approximately three-quarters of the identified mutations." (PMID 33297970, 2020).
mitochondrial disease (2 papers, 2021 to 2023). "Defects in sarcomere genes, such as MYH7, MYBPC3, TNNT2, TPM1, ACTC1, and TTN have been reported as causative for LVNC and LVNC is also commonly associated with mitochondrial diseases." (PMID 37186429, 2023).
muscular disorders (1 paper, 2024). "Unexpectedly, we identified eight patients with pathogenic variants in genes associated with muscular disorders, including MYH3, MYH7, ALPK3, and RYR1." (PMID 38321032, 2024).
musculoskeletal disorders (1 paper, 2024). "We observed that MYH7, RYR1, FBN1, TNNT1, MYBPC1, COL1A1, and CHRNB1 were related to musculoskeletal disorders." (PMID 38658807, 2024).
MYH7 also shares sentences with these, for which no sentence is quoted: hypertrophy (8 papers); familial hypertrophic cardiomyopathy (6); congenital heart disease (4); Left ventricular noncompaction cardiomyopathy (4); long QT syndrome (4); Ventricular hypertrophy (4); Brugada syndrome (3); familial dilated cardiomyopathy (3); familial hypercholesterolemia (3); muscle disorders (3); muscular dystrophy (3); sudden cardiac death (3); ventricular septal defect (3); autosomal dominant disease (2); COVID-19 (2); epilepsy (2); glioma (2); Left ventricular dilatation (2); Marfan syndrome (2); Mitral regurgitation (2); acute myocardial infarction (1); anemia (1); aortic stenosis (1); asymmetrical septal hypertrophy (1); autosomal dominant dilated cardiomyopathy (1); Bethlem myopathy (1); Bicuspid aortic valve (1); Cachexia (1); calcification (1); cardiovascular malformation (1).
A further 73 diseases each share a sentence with MYH7 in 1 paper.